CD8A (CD8 subunit alpha)
Diseases named in the same sentence as CD8A in open-access papers (continued):
Sharing a sentence is not in itself a finding about the gene and the disease.
ischemia (19 papers, 2013 to 2025). A hypoperfusion of the BLOOD through an organ or tissue caused by a PATHOLOGIC CONSTRICTION or obstruction of its BLOOD VESSELS, or an absence of BLOOD CIRCULATION. "On day 14 after the induction of ischemia, CD8a−/− mice exposed to IFN‐γ loading (CD8a−/−‐rIFN‐γ mice) had markedly lowered blood perfusion and capillary density than CD8a−/−‐Saline mice, which suggests that IFN‐γ lessened the angiogenesis in response to hypoxia." (PMID 41243839, 2025). "One study showed that depleting CD8+ T cells by using a CD8α blocking antibody alleviates infarct volume and behavioral deficits in both transient middle cerebral artery occlusion (tMCAO) and permanent MCAO ischemia model mice." (PMID 38077952, 2023). "On post‐ischemia day 14, representative images and the combined quantitative immunoblotting data demonstrated that the ischemic muscles had elevated levels of VEGF and its downstream Erk1/2 phosphorylated proteins in the CD8a+/+ mice, and this signaling activation was augmented in the CD8a−/− mice." (PMID 41243839, 2025).
Cerebral ischemia (18 papers, 2011 to 2025). Restriction of arterial blood supply to the brain associated with insufficient oxygenation to support the metabolic requirements of the tissue. "Regarding the atrophy of lymphoid organs, histological assessment showed that the number of CD8α+ cytotoxic T cells rapidly declined in their cell-rich region and the number of apoptotic cells increased in the spleen and lymph nodes after cerebral ischemia." (PMID 29717383, 2018). "In the BMSC group, these immune changes after cerebral ischemia, that is, a decrease in CD8α+ cells, an increase in TUNEL+ cells, tissue atrophy in the lymphoid organs, and a decrease in Iba1+ macrophages at 14 days in the thymus, were dramatically suppressed." (PMID 29717383, 2018).
chlamydial infection (18 papers, 2008 to 2025). "Regardless of chlamydial infection, expression of CD62L was almost twice as high on CD8αhi as on CD8αdim and CD8α- cells." (PMID 26252769, 2015).
osteoarthritis (18 papers, 2012 to 2025). A noninflammatory degenerative joint disease occurring chiefly in older persons, characterized by degeneration of the articular cartilage, hypertrophy of bone at the margins and changes in the synovial membrane. "Even two shared lncRNA–mRNA interaction pairs in osteoarthritis and osteolysis (AC111000.4 and AC016831.6) may function in the immune process of osteoarthritis and osteolysis by regulating lymphocyte CD8A and CD8B, respectively." (PMID 38106424, 2023).
rectum adenocarcinoma (17 papers, 2016 to 2025). An adenocarcinoma arising from the rectum. "For colon and rectum adenocarcinoma, we find higher levels of CD4, CD8A, and PD-1 in cytomegalovirus-positive tumors than in virus-negative tumors, though other T-cell genes only showed modest differential expression in cytomegalovirus-positive and virus-negative tumors." (PMID 30911684, 2019).
Glucose intolerance (16 papers, 2011 to 2026). Glucose intolerance (GI) can be defined as dysglycemia that comprises both prediabetes and diabetes. "Reconstituting Cd8a−/− mice with CD8+ T cells increased M1 macrophage infiltration into the VAT, proinflammatory gene expression, glucose intolerance, and IR." (PMID 26146464, 2015).
Hepatic steatosis (16 papers, 2018 to 2025). Steatosis is a term used to denote lipid accumulation within hepatocytes. "The plasma levels of CCL23 and CD8A have also been associated with hepatic steatosis." (PMID 34694070, 2021).
cerebral infarction (15 papers, 2013 to 2025). An ischemic condition of the brain, producing a persistent focal neurological deficit in the area of distribution of the cerebral arteries. "Immunohistochemical analysis showed the appearance of and gradual increase in CD8α+ T cells in cerebral infarction after MCAO." (PMID 29717383, 2018).
Fever (15 papers, 2007 to 2026). Body temperature elevated above the normal range. "Similar patterns of CD25 and CD62L expression on classical swine fever virus-specific CD8α+CD4- T-cells were observed after immunisation with the C-strain live attenuated classical swine fever vaccine." (PMID 35891467, 2022).
renal fibrosis (15 papers, 2015 to 2024). A final common manifestation of a wide variety of chronic kidney diseases characterized by glomerulosclerosis and tubulointerstitial fibrosis. "In this study, we identified that depletion of CD8 T cells using anti-CD8α mAb could significantly attenuate PTCs rarefaction and consequent renal fibrosis." (PMID 38904017, 2024).
synovial sarcoma (15 papers, 2014 to 2025). "Furthermore, we found that synovial sarcoma, which overexpresses PRAME, showed a significantly lower B2M and CD8A expressions compared to other subtypes." (PMID 28630682, 2017).
esophageal adenocarcinoma (13 papers, 2012 to 2024). A malignant tumor with glandular differentiation arising predominantly from Barrett mucosa in the lower third of the esophagus. "Significant lower infiltration of CD8 T cells and M1 macrophages and a lower expression of CD8A, CD8B, and TBX21 were found also in Esophageal Adenocarcinoma TCGA panCancer Atlas in the normal tissue of patients with nodal metastasis." (PMID 36281585, 2023).
enteropathy (12 papers, 2011 to 2025). "Inflammatory markers were also up-regulated in SBM-induced enteropathy in the distal intestine of Atlantic salmon, and the prevention of SBM-induced enteritis by BM was related to intestinal levels of MHCII- and CD8α-reactive cells." (PMID 27898676, 2016).
abscesses (10 papers, 2009 to 2025). "However, only very few single apoptotic DCs (CD11c+TUNEL+) were found in Yersinia-induced abscesses in the spleen of infected mice, and total numbers of 7-AAD+ CD4+ and CD8α+ DCs were unaltered upon Ye infection and in PBS-treated control mice." (PMID 21124820, 2010).
dry eye (9 papers, 2012 to 2025). "We have previously reported that our experimental dry eye model causes an influx of pathogenic CD4+T cells, and a significant decrease in CD8α cells in the conjunctival epithelium when these cells are counted infiltrating the goblet cell rich area." (PMID 22590618, 2012).
scrub typhus (9 papers, 2011 to 2023). Scrub typhus is a rare dust mite-borne infectious disease caused by the Orientia tsutsugamushi bacterium and characterized clinically by an eruptive fever which is potentially serious. "The transcriptional signature of patients with scrub typhus included the differential expression of the CBLB, LOC642161, CD8A, CD8B1 and FOSB genes, when compared to healthy controls and patients with other infectious diseases." (PMID 21610853, 2011).
seminoma (9 papers, 2014 to 2025). A radiosensitive malignant germ cell tumor found in the testis (especially undescended), and extragonadal sites (anterior mediastinum and pineal gland). "The molecular distinction between seminomas and teratomas enables tailored therapeutic approaches: in seminomas, synthetic hsa-miR-138-5p mimics could reinforce apoptotic and anti-inflammatory pathways, while PD-1/PD-L1 checkpoint inhibitors may overcome STAT1- and CD8A-driven immune escape." (PMID 40869426, 2025).
Yersinia infection (8 papers, 2010 to 2022). "Interestingly, the Yersinia infection significantly reduced the proliferation of the OVA-specific CD4+ T cells co-cultured with OVA protein (p = 0.0047) or peptide-pulsed (p = 0.037) CD8α+ DCs." (PMID 21124820, 2010). "Interestingly, CD8α+ DCs produced less IL-12 and TNF upon Yersinia infection, indicating that Ye specifically targets this cDC subset." (PMID 21124820, 2010).
chronic pancreatitis (7 papers, 2020 to 2025). A chronic inflammatory process causing damage and fibrosis of the pancreatic parenchyma. "We could show that CD8α+ cells are located in chronic pancreatitis tissue of mice and their number is increased in Treg depleted mice." (PMID 35922425, 2022).
immunotoxicity (7 papers, 2009 to 2023). "Five genes (CD8A, CYP1A1, ITGAX, LYZ, and PTPRC) associated with immunotoxicity were among the most up‐regulated genes exposed to dose 1:8 indoor PM." (PMID 31883508, 2020).
adenomyosis (6 papers, 2022 to 2025). The growth of endometrial tissue inside the muscular wall of the uterine corpus. "This occurrence was corroborated by immunohistochemical staining for CD4 (a marker of CD4+ T cells), CD8α (a marker of CD8+ T cells), and CD11c (a marker of DCs), which showed high protein levels at the invaginating site of adenomyosis." (PMID 40190183, 2025).
vaginal infection (6 papers, 2011 to 2024). "After vaginal infection, CD103+ NK1.1+ CD8α- cells expand among circulating CD11c+ T cells and CD8α+ CD103- NK1.1- are elevated in the GT." (PMID 27119555, 2016).
E. coli infection (4 papers, 2021 to 2024). "Moreover, the results demonstrate the expression of the cytokines IL-1β and IL-6, cell mediated responses as well as APEC-specific T-cell response dominated by IFN-γ-producing CD8α+ and TCR-γδ+ subsets to be triggered against colibacillosis." (PMID 37261344, 2023).
erythroleukemia (4 papers, 2012 to 2025). Acute erythroid leukemia characterised by the presence of at least 50% erythroid precursors and at least 20% myeloblasts in the bone marrow. "The results indicated that D-EDA significantly increased the expression of CD4, CD8a, and B220, suggesting enhanced immune cell activation and improved immune function in erythroleukemia mice." (PMID 40362240, 2025). "Moreover, this study further revealed that D-EDA alleviated the burden on the spleen and liver, restored spleen structure, enhanced the differentiation of Ter119+, CD4+, CD8a+, and B220+ cell populations, and effectively prolonged the survival of erythroleukemia mice in vivo." (PMID 40362240, 2025). "Moreover, the proportions of CD4, CD8a, and B220 cells in erythroleukemia spleen also increased significantly in the H-120 treatment group, indicating that H-120 effectively stimulates the immune cells in erythroleukemia mice." (PMID 38611876, 2024).
parasitism (4 papers, 2012 to 2025). "Since Cd8a−/− micepresented higher susceptibility to N. caninum infection than their WTcounterparts, CD8+ T cells are likely able to provide immuneprotection against this parasite infection." (PMID 26449650, 2015).
gallbladder adenocarcinoma (3 papers, 2003 to 2021). A carcinoma that arises from glandular epithelial cells of the gall bladder. "To validate the scRNA‐seq results, we analyzed independent gallbladder adenocarcinoma and adjacent normal tissues by immunohistochemistry (IHC) staining and found a significant increase of FOXP3+ or CD4+ cells and a reduction of CD8A+ cells in tumors." (PMID 34185421, 2021).
retinoblastoma (3 papers, 2020 to 2022). A malignant tumor that originates in the nuclear layer of the retina. "Furthermore, in retinoblastoma and UVM, CD8A manifested significant negative correlations with two and twelve functional states, respectively, while only showing a positive correlation with quiescence in BRCA." (PMID 36035168, 2022).
blastomycosis (2 papers, 2018 to 2023). Blastomycosis is a rare infection that may develop when people inhale a fungus called Blastomyces dermatitidis, a fungus that is found in moist soil, particularly where there is rotting vegetation. "Not surprisingly, PMN-DCs during early blastomycosis did not express CD8a or langerin found on DCs in lymphatic and skin tissue, respectively." (PMID 29782541, 2018).
bronchopulmonary dysplasia (2 papers, 2021 to 2024). Bronchopulmonary dysplasia is a chronic respiratory disease that results from complications related to lung injury during the treatment of infant acute respiratory distress syndrome in low-birth-weight premature infants or from abnormal lung development in older infants. "CD8a expression is downregulated in a model of bronchopulmonary dysplasia." (PMID 39075660, 2024).
Cholecystitis (2 papers, 2022 to 2025). The presence of inflammatory changes in the gallbladder. "Notably, we identified a subset of eight plasma proteins (PAHX, CD8A, HRG, CRIS2, Dynactin subunit 2, AT2A3, CSTN2, and DEPP) that effectively differentiated GBC from cholecystitis with a diagnostic accuracy of 94% when validated on a test set." (PMID 40470116, 2025).
pericarditis (2 papers, 2024). An inflammatory process affecting the pericardium. "There have been some studies on CCL2, CD8A, and PTPRC in cardiovascular diseases; however, their roles in pericarditis require further research." (PMID 38455049, 2024).
C. perfringens infection (1 paper, 2023). "However, C. perfringens infection resulted in a significant reduction in intestinal CD4+ αβ T cell while an increase in CD8α + αβ T cell was observed thereby shifting this ratio to 5:1, proportionally more in favor of CD8α + αβ T cells." (PMID 38164397, 2023). "However, the combination of rL. lactis treatment and subsequent C. perfringens infection resulted in the increase of both CD3ζ + CD4+ and CD3ζ + CD8α + αβ T across the intestine when compared to the infected or control chickens, respectively." (PMID 38164397, 2023). "While these two cell types are well adapted to intestinal stimuli and perform their functions in protecting the delicate epithelial layer, the role of CD8α + αβ T cell in mucosal tissues against C. perfringens infection, an extracellular pathogen, is not understood." (PMID 38164397, 2023).
dysentery (1 paper, 2008). Acute inflammation of the intestine associated with infectious diarrhea of various etiologies, generally acquired by eating contaminated food containing toxins, biological derived from bacteria or other microorganisms. "We have previously reported on the increase of numbers of neutrophils, monocytes and CD8α+ lymphocytes during dysentery and the increase in γδ T cells and B. hyodysenteriae-specific antibodies during the recovery period." (PMID 18700003, 2008). "IFN-γ is an activator of the cytotoxic T cell pathway and may be of interest during swine dysentery in view of the increase in CD8α+ T and/or NK cells that has previously been reported to occur during dysentery." (PMID 18700003, 2008).
intraductal papillary mucinous neoplasms (1 paper, 2020). "The percentage of CD8A-positive T lymphocytes expressing HAVCR2 and/or PDCD1 was lower in cases of intraductal papillary mucinous neoplasms (IPMN) and serous cystadenoma (SC) compared to the percentage observed in PDAC." (PMID 32645996, 2020).
skin changes (1 paper, 2024). "The gene sets encompass numerous genes previously implicated in the pathogenesis of SSc, such as Acta2, Col1a1, Col3a1, Smad3, Ctgf, Msr1, Cd4, Cd8a and Cd68, supporting the potential of anti-PRMT5 in induction of SSc-like skin changes." (PMID 38684324, 2024).
tumor (36,424 papers, 1990 to 2026). "Based on the loss of CD8a+ T cells in the MTCQ1 tumor microenvironment on day 3 post 2 Gy x 6 EBRT, therapeutic studies to monitor tumor control and animal survival were designed." (PMID 41141655, 2026). "Transcriptomic profiling further revealed elevated Cd8a and Ifng (markers of cytotoxic T cell infiltration/activity) alongside reduced Foxp3 (Tregs), Cd163 (M2-polarized tumor-associated macrophages), and Tgfb1 (immunosuppressive cytokine) in KO tumors." (PMID 41144132, 2025). "Overall, increased M1-polarization in breast tumors of genetic and inducible RON loss models, as well as increased CD8a T cell presence, suggests an anti-tumor microenvironment when RON is lost in the macrophages." (PMID 40282397, 2025). "In periampullary and pancreatic adenocarcinoma, a detailed in situ description of lymphocyte infiltration patterns showed that the proximity of CD8α + cells to tumor cells was associated with overall survival." (PMID 38918817, 2024). "The evaluation of estimated cell fractions showed that some suppressive immune signatures, such as regulatory T cells (Tregs), CD8A+ exhausted T cells, and tumor-associated macrophages (TAMs), exhibited higher infiltration in the CS1 subtype." (PMID 39513109, 2024). "Both protein levels determined by IHC and mRNA levels determined by RT-qPCR of tumor tissues showed that higher TIM expression was associated with lower CD8a expression." (PMID 37340461, 2023). "We found that TMEM41A overexpression was correlated with EC stromal, immune, and estimate scores and was linked with tumor purity, immune cells (such as the macrophages, CD8 T cells, and TFH), and immune cell markers (such as the CD8A, CD3D, and CD3E)." (PMID 37478120, 2023). "CD8A expression was highly related to tumor mutation burden, critical immune checkpoint genes and several types of tumor-infiltrating immune cells, predicting effective response to immunotherapy." (PMID 36230788, 2022). "Our results showing an increase in the alpha subunit of CD8 (CD8A) being significantly associated with longer PFS in the TT patient group can be an indication of the importance of tumor-directed immunity in TT." (PMID 35892846, 2022). "Priming and activation of CD8+ antitumour T cell responses against solid tumors require cross-presentation of tumor-associated antigens (TAAs) by cDC1 especially migratory CD103+ and lymphoid CD8α+ DCs46–49." (PMID 36463242, 2022). "CAR was comprised of three main domains: a tumor associated antigen binding region, CD8α hinge and transmembrane region, and 4-1BB and CD3z intracellular motif." (PMID 34980210, 2022). "Mouse cDC1s cross-present exogenous or tumor-associated antigens to CD8α+ T cells through MHC class I molecules as well as secrete IL-12." (PMID 35454882, 2022). "Based on the GDSC database, we then examined associations between CD8A and sensitivity and responsiveness of tumor cell lines to various antitumor agents or compounds." (PMID 36035168, 2022). "CD8α+ T cells were only rarely observed in the tumor microenvironment of STING-sufficient or -deficient TRAMP-C2 tumors." (PMID 33790360, 2021). "Accordingly, expression of genes encoding IFNγ, CD8α and CD8β was significantly increased in tumor samples with a low TSP1 expression." (PMID 34439212, 2021). "The increase in neoantigens and duration of survival with disease tends to be associated with increased CD3+ CD8+ density in the tumor and CD8A expression." (PMID 33796222, 2021). "And the activated CD8α+ DCs engulfed apoptotic tumor material and cross presented tumor-associated antigen to naïve CD8+ T cells, which induced cytotoxic T lymphocyte (CTL) mediated lysis." (PMID 33214545, 2020). "CD8α+/CD103+ are the migratory DCs that excel in transporting tumor-associated antigens (TAAs) to the lymph nodes in a CCR7-dependent manner." (PMID 32132993, 2020).